TRIB2 (tribbles pseudokinase 2)
Diseases named in the same sentence as TRIB2 in open-access papers (continued):
Sharing a sentence is not in itself a finding about the gene and the disease.
cancer (continued). "Taken together, these results reveal that TRIB2 promotes cancer cells growth and suppresses cellular senescence via enhancing AP4 transcription activities." (PMID 30541550, 2018). "Functionally, depletion of TRIB2 inhibited cancer cells proliferation, induced cell cycle arrest and promoted cellular senescence, whereas overexpression of TRIB2 accelerated cell growth, cell cycle progression and blocked cellular senescence." (PMID 30541550, 2018). "Down-regulation of TRIB2 inhibited cancer cells proliferation, induced cell cycle arrest and promoted senescence in CRC cells." (PMID 30541550, 2018). "IPA analysis of these unique up-regulated genes indicated that some genes were associated with cell transformation during cancer progression (ABL1, TRIO, FOSB, NRCAM, TRIB2 and CDK6) and others with cell survival (e.g., BCL10, BBC3, FGF8, HSPA4 and SOD1)." (PMID 29137349, 2017). "Our findings provide a novel vertebrate cell cycle link between TRIB2 and CDC25C, and suggest regulated TRIB2 functions during the cell cycle that are likely to be important in cancer." (PMID 27563873, 2016). "The overexpression of TRIB2 was observed in cancer cells, where regulation of growth arrest is altered." (PMID 24834131, 2014). "This is consistent with the data obtained in human concerning TRIB1 in blood T-cells, for TRIB2 in LT7 cancer cells and for TRIB3 in Muller cells." (PMID 24834131, 2014). "To date, no specific TRIB2-targeted agents have entered clinical trials for the treatment of TRIB2-associated cancers." (PMID 39520729, 2025). "It's now well known that harmine may be the best option to defeat TRIB2-based therapy resistance, providing an effective way to enhance clinical outcomes for cancer patients." (PMID 39954215, 2025). "Consequently, the development of TRIB2-targeting PROTACs represents a highly promising avenue for novel cancer therapies." (PMID 39520729, 2025). "Regarding TRIB2, it can function as an oncogene, regulating a wide range of cellular processes, including tumorigenesis, proliferation, invasion, and chemoresistance in various cancer subtypes." (PMID 38794149, 2024). "The HLM score was constructed based on six genes, AGXT, TRIB2, ELFN2, PCDHB10, CALCA, and CD79A, which have been previously reported to be associated with the tumorigenesis and progression of various cancer types, including CRC, as well as chemotherapy resistance." (PMID 38902737, 2024). "Among the 7 RNA, CDC73 and TRIB2 have been identified as biomarkers for cancer prognosis." (PMID 35751033, 2022). "In general, Trib2 is considered as a “pseudokinase”, contributing to different kinds of cancer." (PMID 35790734, 2022). "To date, the detailed roles of TRIB2 in cancer and the function of “pseudokinase domain” remain unclear." (PMID 35790734, 2022). "As an important regulator of iron uptake, TFR1 undergoes ubiquitination and degradation by β-TRCP E3 ligase in a tribbles pseudokinase 2 (TRIB2)-dependent manner, consequently blocks ferroptosis in live cancer cells, but how does TRIB2 affect βTRCP-mediated TFR1 degradation?" (PMID 36289191, 2022). "Either PKM2 or TRIB2 overexpression increased cancer cell proliferation and migration." (PMID 35790734, 2022). "In summary, we found that TRIB2 may have phosphorylated kinase activity to directly phosphorylate PKM2 at serine 37 in cancer cells." (PMID 35790734, 2022).
cancer (continued). "Owing to its importance in tumorigenesis and therapeutic resistance, targeting TRIB2 may present an exciting opportunity for cancer therapy and anti-cancer drug design." (PMID 35790734, 2022). "Moreover, the levels of HIF-1α, Cyclin D1, c-Myc, and OCT4 were elevated in TRIB2-overexpressed cancer cells, which further promote cancer cell proliferation." (PMID 35790734, 2022). "We observed that TRIB2 overexpression increased the RFWD2 levels in cancer cells, indicating that the regulating action of TRIB2 may be related to its interaction with and effect on RFWD2." (PMID 34646775, 2021). "Hence, TRIB2 can be a novel targeted therapeutic and strong candidate against chemoresistant cancers." (PMID 33794905, 2021). "The study of the mechanisms that regulate TRIB2 during the cell cycle might shed light on how its deregulation leads to diseases such as cancer." (PMID 34070799, 2021). "Although TRIB2 has been reported to modulate p38,34 p38 inhibition did not abrogate the anisomycin‐induced phosphorylation of HDAC2 in ESCC cells, suggesting that the effect of TRIB2 on the MAPK pathway might be cancer‐dependent." (PMID 34586732, 2021). "In addition, there is solid evidence that TRIB2 expression affects the sensitivity of cancer cells to chemotherapeutic and targeted anticancer drugs." (PMID 34070799, 2021). "TRIB2, an atypical protein kinase, regulated the progression of cancers." (PMID 34030715, 2021). "The identified compounds or similar molecules might have the potential to attenuate TRIB2-mediated therapy resistance in several human cancers." (PMID 33316942, 2020). "Our data suggest that harmine and piperlongumine or similar compounds might have the potential to overcome TRIB2-mediated therapy resistance in cancer patients." (PMID 33316942, 2020). "Our results highlight the great potential of this approach for drug repurposing and suggest that harmine and piperlongumine or similar compounds might be useful in the clinic to overcome TRIB2-mediated therapy resistance in cancer patients." (PMID 33316942, 2020). "Both high and low Trib2 expression levels correlate with different types of cancer." (PMID 29670085, 2018). "Currently, the role of TRIB2 in cancer remains controversial." (PMID 30541550, 2018). "We speculated that TRIB2 may have distinct functions depending on etiologic background of different cancer types." (PMID 30541550, 2018). "The knockdown of TRIB2 leads to cell cycle arrest and apoptosis of the cancer cells." (PMID 29599919, 2018). "The contribution of Tribbles isoforms in mammals to insulin regulation and cancer is complex: recently, TRIB2 has been shown to be an Akt agonist, and an R107L mutation in TRIB1 that aligns with R141Q in TRIB3 promotes leukemogenesis by enhancing ERK phosphorylation and C/EBPα degradation." (PMID 29025897, 2017). "The mRNA and protein levels of CCAAT/enhancer binding protein alpha (CEBPA), known to be a transcription factor regulating cell differentiation and a target for degradation by TRIB2, as well as selected cancer stem cell makers in the Cisplatin-resistant cells, were measured." (PMID 29312632, 2017). "The role of TRIB2 in cancer and its potential druggability merit further investigations." (PMID 27613601, 2016). "We found that expression of ADCK2 and TRIB2 mRNA is regulated by TNFα in U2OS cancer cells." (PMID 22355351, 2012). "In addition, TRIB2 overexpression can affect the sensitivity of cancer cells to anti-cancer drugs." (PMID 35790734, 2022). "However, the exact mechanism of TRIB2 as an adaptor protein in cancer is still controversial and remains unclear." (PMID 33794905, 2021). "Therefore, Trib2 may be a suitable biomarker for the cancer diagnosis, because it shows high expression in malignant cells." (PMID 33794905, 2021). "Thus, Trib2 can be a predictive and valuable biomarker for the diagnosis and treatment of cancer." (PMID 33794905, 2021).
cancer (continued). "TRIB2 confers resistance to several anti-cancer therapies and, therefore, pharmaceutical means to interfere with its activity might have the potential to overcome drug resistance and improve clinical outcome in cancer patients." (PMID 33316942, 2020). "In common with TRIB3, a potential link between TRIB2 and HIF-1α has been reported, as depletion of TRIB2 significantly decreased the effect of TNF-α on HIF-1α stability and accumulation in multiple cancer cell lines." (PMID 38896446, 2024). "On the other hand, similar to TRIB2, TRIB3 binds to EGFR and stabilizes its recycling, facilitating the development of cancer." (PMID 38731938, 2024). "So far, there is one only study on TRIB2 in GC, reporting that its level is downregulated in MGC-803 GC cells following treatment with the anti-cancer agent dioscin." (PMID 38254916, 2023). "TRIB1, TRIB2, and TRIB3 have been involved in different cancers including hematological malignancies (mostly TRIB2) and a variety of solid tumors." (PMID 38254916, 2023). "TRIB2 was also characterized to activate Akt and ERK via a still obscure mechanism to support aggressive cancer growth and therapeutic resistance." (PMID 34973338, 2022). "However, the detailed roles of TRIB2 in regulating cancer metabolism by PKM2 remain unclear." (PMID 35790734, 2022). "TRIB2 with PKM2 promotes the Aerobic glycolysis, generating the energy required to support rapid cancer cell proliferation." (PMID 35790734, 2022). "Like TRIB1, TRIB2 represents a still poorly characterized mediator of proliferative signalling pathways, and TRIB2 modulators (such as conformation‐biased inhibitors) may be good therapeutic agents in multiple cancers especially in the context of drug resistance." (PMID 32053275, 2020). "It has also been found to act as a cancer-suppressive miRNA by targeting important oncogenes, such as PIK3R3, TRIB2 and Bax." (PMID 28114950, 2017). "In addition to the METTL14/miR-99a-5p/TRIB2 axis, TRIB2 activates HDAC2 and inhibits HDAC2 (Ser394) phosphorylation through the Akt/mTOR/S6K1 signal pathway in ESCC, thus inhibiting cancer stemness and improving radiation resistance of ESCC cells." (PMID 37522921, 2023). "In this study, TRIB2 is found to interact with PKM2 and may exhibit kinase activity to directly phosphorylate PKM2 at serine 37 in cancer cells." (PMID 35790734, 2022). "TRIB2 also has the kinase activity to directly phosphorylate PKM2 at serine 37 in cancer cells, and the elevated pSer37-PKM2 would promote the dimers to enter into nucleus and to increase the aerobic glycolysis in cancer cells." (PMID 35790734, 2022). "Therefore, similar to other renowned cancer related proteins (e.g. E2Fs, p21, GADD45A, MYC and RUNX1), Trib2 obeys the Goldilocks principle in cancer biology; too little or too much are both pro-tumorigenic." (PMID 29670085, 2018). "These conflicting roles of TRIB2 may be due to the genetics of the AML subtype, the cancer type, and the profile of the apoptotic regulators within those cells." (PMID 29599919, 2018). "We found that CEBPA protein levels could be upregulated by knocking down the overexpressed TRIB2, which also reversed the Cisplatin-resistance of these cells; further, the Cisplatin-resistant SCLC cells demonstrated certain cancer stem cell-like properties." (PMID 29312632, 2017). "Furthermore, our results suggest that four of these genes - ADCK2, PRKAR2B, TRIB2 and TRPM7 - seem to regulate HIF-1α accumulation in multiple cancer cell lines." (PMID 22355351, 2012). "In the absence of kinase activity, TRIB2 functions as a scaffold protein to regulate different signaling pathway in fundamental biological processes as well as in pathological conditions, including cancer." (PMID 30541550, 2018).
cancer (continued). "As well as tribbles pseudokinase 2 (TRIB2) that belongs to a family that controls the specificity of the activation of mitogen-activated protein kinases (MAPK), and its increased expression has been reported in several carcinomas, suggesting an oncogenic function." (PMID 25192291, 2014). "This study demonstrated that TRIB2, not a “pseudokinase”, has the kinase activity to directly phosphorylate PKM2 at serine 37 in cancer cells." (PMID 35790734, 2022). "TRIB2 preferentially binds to catalytically inactive, non-phosphorylated threonine 308 AKT1 in vitro and increases endogenous AKT phosphorylation at the hydrophobic motif (serine 473) in human cancer cells." (PMID 34070799, 2021).
tumor (45 papers, 2012 to 2025). "TUG1 or TRIB2 loss of function prohibited proliferation, migration, invasion along with in vivo tumor growth but facilitated CRC apoptosis." (PMID 36333703, 2022). "This work also revealed a novel tumor suppressor-like function for TRIB2 in the cell cycle and proliferation of early T cell progenitor cells, and associated high levels of TRIB2 expression with early immature T-ALL and deregulated MAPK signaling." (PMID 27908682, 2017). "Trib1 and Trib2 are also implicated as tumor suppressors in some subtypes of AML through inhibition of JNK signaling." (PMID 27191957, 2016). "By different experimental approaches, in both cell lines, we could associate TRIB2 overexpression with suppressed proliferation and colony formation, cell cycle arrest in G2, and reduced migration, thus confirming a tumor-suppressive role of the gene." (PMID 38254916, 2023). "We also found a significant association between TRIB2 expression and tumor grade." (PMID 30541550, 2018). "Among them, TRIB2 exhibited the highest expression level in HB and showed the most significant overexpression difference compared with non-tumor tissues, establishing it as the top-priority oncogenic driver candidate for further investigation.​." (PMID 41462308, 2025). "In this study, we present the first comprehensive characterization showing that SE-driven TRIB2 expression is mediated through tumor-specific E-P looping, with TCF3 acting as an activator of this mechanism to drive HB pathogenesis." (PMID 41462308, 2025). "Functionally, TRIB2 promoted cell proliferation and accelerated tumor growth both in vitro and in vivo." (PMID 41462308, 2025). "This mechanistic divergence underscores two tumor-type-specific functions of TRIB2: regulation of iron metabolism through TFRC degradation in HCC, and control of redox homeostasis via the KEAP1-NRF2 pathway in HB." (PMID 41462308, 2025). "In this study, integrative multi-omics profiling of HB and matched non-tumor tissues identified TRIB2 as an SE-driven oncogene that promotes HB malignancy both in vitro and in vivo." (PMID 41462308, 2025). "3C-qPCR analysis detected enhanced interactions between the TRIB2 promoter and enhancer elements in HB compared with non-tumor tissue." (PMID 41462308, 2025). "Chromatin loop analysis identified 4,168 HB-specific and 4,009 non-tumor-specific chromatin interactions, anchoring 187 DEGs, including TRIB2, SERPINE2, and MYCN." (PMID 41462308, 2025). "One study discovered that TRIB2 impedes tumor cell senescence, stimulates proliferation, and triggers cell cycle arrest via AP4/p21 signaling in CRC." (PMID 38902737, 2024). "In contrast, TRIB2 has been reported to be a regulator of thymocyte proliferation with tumor suppressor functions, important for the thymopoietic response to genotoxic and oncogenic stress." (PMID 38254916, 2023). "Altogether, our results point to a tumor-suppressive function of TRIB2 in GC with a CIN molecular phenotype, identifying TRIB2 as a possible novel player in CIN GC tumorigenesis." (PMID 38254916, 2023). "We correlated TRIB2 gene expression (high vs. low/intermediate) with patients’ sex, tumor histologic grade, and tumor stage." (PMID 38254916, 2023). "To search for downstream targets mediating the tumor-suppressive effects of TRIB2 in CIN GC cells, we checked for the activation of AKT and ERK upon TRIB2 overexpression." (PMID 38254916, 2023). "We also found overexpression of NE markers and downregulation of AR in TRIB2-OE cells in tumor xenografts in mice." (PMID 34973338, 2022). "significantly increased expression of TRIB2 in tumor tissue correlates with increased phosphorylation of AKT, FOXO3a, MDM2 and impaired treatment response." (PMID 36300089, 2022). "Though there is accumulated evidence that all members of the TRIB protein family are involved in normal physiology, in this review we will focus on the specific role of TRIB2 in tumour formation, progression and therapy resistance." (PMID 34070799, 2021).